S100A8 (S100 calcium binding protein A8)
Diseases named in the same sentence as S100A8 in open-access papers (continued):
Sharing a sentence is not in itself a finding about the gene and the disease.
diabetes (continued). "Taken together, our novel data suggest that pharmacological blockade of S100A8/A9 may represent a promising cardioprotective strategy in cancer patients with history of diabetes, thus restoring the therapeutic value of doxorubicin in these patients." (PMID 27547188, 2016). "Diabetic nephropathy (DN), a severe complication of diabetes and a leading cause of end-stage renal disease, is strongly associated with chronic inflammation triggered by damage-associated molecular patterns (DAMPs), such as high-mobility group box 1 (HMGB1), S100A8, and S100A9." (PMID 41367913, 2025). "Further, stimulation of skin cultures with TNF and IL-1β, but not with diabetes-associated factors like insulin and glucose, stimulate S100A8 and A9 expression in the skin, supporting the previous notion of an inflammatory-driven pathological overexpression of S100A8 and A9." (PMID 39337466, 2024). "It has been demonstrated that the S100A8 profile correlated closely with levels of systemic inflammatory markers and the severity of CAD in patients with diabetes." (PMID 35365066, 2022). "We see, for example, that S100A8/A9 are both increased in the DPN donors, where elevated circulating levels of these proteins can act as a biomarker for diabetes-induced inflammation." (PMID 35304484, 2022). "Moreover, a recent study in obese patients with or without type 2 diabetes mellitus (T2DM) showed that plasma S100A8/A9 was significantly reduced following Roux-en-Y gastric bypass surgery independent of diabetes." (PMID 31249530, 2019).
myocardial infarction (42 papers, 2012 to 2026). Gross necrosis of the myocardium, as a result of interruption of the blood supply to the area, as in coronary thrombosis. "Subsequent enrichment analysis singled out S100A8/A9 for in-depth examination due to its established association with inflammation and its crucial role in myocardial infarction." (PMID 40977740, 2025). "Recent investigations have unveiled a direct association between S100A8/A9, inflammation onset, and cardiac damage post-myocardial infarction." (PMID 40977740, 2025). "A positive association has been observed between serum S100A8/A9 levels and neutrophil counts in patients with Acute myocardial infarction (AMI) who are under dynamic monitoring." (PMID 39175627, 2024). "Here, we show that S100A8/A9 is a predictor and potentially causal medicator for heart failure post-acute myocardial infarction." (PMID 38538601, 2024). "Acute-phase inhibition of the pro-inflammatory alarmin S100A8/A9 improves cardiac function post-myocardial infarction (MI), but the mechanisms underlying the long-term benefits of this short-term treatment remain to be elucidated." (PMID 39009944, 2024). "S100A8/9 can also be used as a prognostic diagnostic and therapeutic target for myocardial infarction." (PMID 36659877, 2023). "S100a8 and S100a9 can also cause stent thrombosis in the very late stage of acute myocardial infarction." (PMID 35741040, 2022). "Patients with elevated S100A8/A9 had a significantly increased risk of death and myocardial infarction." (PMID 35795659, 2022). "Increased plasma S100A8/A9 levels have been associated with atherogenesis, plaque vulnerability, myocardial infarction (MI), cardiovascular death, and heart failure." (PMID 29379499, 2017). "Plasma levels of S100A8/A9 predicted risk of future myocardial infarction, stroke or death in post-menopausal healthy women." (PMID 26792056, 2016). "S100A8/A9 is locally released following myocardial infarction and amplifies the inflammatory responses associated with myocardial ischemia/reperfusion injury." (PMID 24453429, 2013). "Elevated plasma levels of S100A8/A9 are associated with increased risk of future coronary events in healthy individuals and in myocardial infarction survivors." (PMID 24453429, 2013). "Here, the authors show that circulating S100A8/A9 is a robust predictor and potentially causal medicator for heart failure post-acute myocardial infarction, as such could serve as a promising drug target for cardioprotection." (PMID 38538601, 2024). "Meanwhile, elevated serum S100A8/A9 levels 1 day after percutaneous coronary angioplasty (PCI) were found to be significantly associated with long-term adverse cardiovascular events in patients with acute myocardial infarction in the clinic." (PMID 39175627, 2024). "Moreover, neutrophils activated by S100A8/A9 after myocardial infarction are implicated in NETosis, the inflammatory cell death mode of neutrophils." (PMID 37217870, 2023). "Furthermore, novel biomarkers such as S100A8/A9—previously investigated in post-acute myocardial infarction HF—may further enhance risk stratification when combined with the established risk factors." (PMID 40075836, 2025). "Pioneering research into mechanistic insights on S100A8/A9 contribution to the progression of ischemic HF was performed on murine myocardial infarction models." (PMID 40948795, 2025). "Blocking S100A8/A9 is a crucial factor in promoting cardiac recovery following myocardial infarction." (PMID 40948795, 2025). "In the setting of sterile inflammation such as ischemic stroke and myocardial infarction the functional contribution of S100A8/A9 awaits further elucidation in appropriate animal models." (PMID 40656637, 2025). "In several inflammation-related diseases, such as myocardial infarction, acute lung injury, acute kidney injury, and cancer, S100A8/A9 were reported to be valuable biomarkers." (PMID 40270593, 2025).
myocardial infarction (continued). "In myocardial infarction there is evidence that neutrophil-derived S100A8/A9 contributes to perpetuation of inflammation, myocardial injury but also resolution of inflammation." (PMID 40656637, 2025). "A recent study evaluated S100A8/A9 levels in patients with acute myocardial infarction and their relationship with de novo HF during 4.2 years of follow-up." (PMID 40948795, 2025). "Sreejit and collaborators demonstrated on a mouse model of myocardial infarction that neutrophil-derived S100A8/A9 amplifies acute inflammation, by stimulating myeloid progenitor cells in the bone marrow, which lead to enhanced granulopoiesis." (PMID 40948795, 2025). "Short-term pharmacologic blockade (3 days) of S100A8/A9 after myocardial infarction significantly reduces acute inflammatory cell infiltration and tissue damage, improving early and long-term cardiac function." (PMID 40948795, 2025). "Recent studies have demonstrated that circulating neutrophils were rapidly activated and recruited to the injured myocardium after myocardial infarction, releasing S100A8/S100A9 locally in the ischemic microenvironment." (PMID 38062310, 2025). "Prolonged or extended blockade (>7 days post-myocardial infarction) of S100A8/A9 has adverse effects, such as impaired monocyte/hematopoietic stem cell responses, reduced reparative/fibrotic macrophage recruitment, and deterioration of cardiac function." (PMID 40948795, 2025). "Elevated S100A8/A9 levels have been observed in patients with myocardial infarction and deep vein thrombosis." (PMID 40656637, 2025). "S100A8/A9 has been recognized as a new predictor for myocardial infarction, with incremental increases in S100A8/A9 protein levels associated with a proportional rise in the risk of subsequent cardiovascular events." (PMID 39175627, 2024). "S100A8/A9 exerts a harmful influence during the initial phase of myocardial infarction (MI), and interventions aimed at inhibiting S100A8/A9 can be advantageous for MI patients." (PMID 39175627, 2024). "In response to myocardial infarction, a surge of neutrophils expressing the alert protein S100A8/A9 rapidly infiltrates the ischemic myocardium." (PMID 39175627, 2024). "Elevated release of S100A8/A9 appears to exert deleterious effects during myocardial infarction and is linked to an unfavorable long-term prognosis, while the inhibition of S100A8/A9 has been effective in myocardial infarction models." (PMID 38667035, 2024). "S100A8/A9 contributes to the regulation of both phases of myocardial infarction, with a particular impact on the migratory and differentiative behaviors of immune cells." (PMID 39175627, 2024). "S100A8/A9 plays a primary role in triggering inflammatory response after myocardial infarction since this complex is highly expressed in angiotensin II-stimulated neutrophils, where it accounts for 45% of cytoplasmic protein." (PMID 37217870, 2023). "Neutrophil‐derived S100a8/a9 has recently been demonstrated to promote granulopoiesis/myelopoiesis in the bone marrow after myocardial infarction." (PMID 38023700, 2023). "Genetic and pharmacological strategies aiming at blockade of the S100a8/a9‐Nlrp3‐IL‐1β signaling axis have been shown to dampen myelopoiesis and improve cardiac function after myocardial infarction." (PMID 38023700, 2023). "Recent research has shown similar findings that serum S100A8/A9 levels were elevated in 178 CAD patients with unstable angina pectoris or acute myocardial infarction, and the level of S100A8/A9 was significantly positively linked with CRP (P < 0.01)." (PMID 29379499, 2017). "A case-control study of 237 patients identified a recurrent cardiovascular event, cardiovascular death or myocardial infarction occurred more after acute coronary syndrome in high level S100A8/A9." (PMID 26914918, 2016). "Increased platelet S100A8 mRNA and plasma protein levels were present in patients with acute myocardial infarction." (PMID 26792056, 2016).
myocardial infarction (continued). "In the early phase of myocardial infarction, S100A8/A9 released from neutrophils leads to the activation of proinflammatory signaling pathways, such as NF-κB or MAPK, that recruit additional inflammatory cells and promote the release of inflammatory cytokines, amplifying the inflammatory response." (PMID 40948795, 2025). "Furthermore, elevated serum levels of S100A8/A9 correlate with major adverse cardiac events in myocardial infarction patients." (PMID 40977740, 2025). "However, previous studies have reported that neutrophils were the primary source of S100A8/A9 in myocardial infarction and that these proteins affected mitochondrial complex I function, inducing cardiomyocyte apoptosis." (PMID 40270593, 2025). "Nonetheless, S100A8/A9 has a limited diagnostic utility, with a sensitivity of 28% for myocardial infarction in patients presenting with non-traumatic chest pain, and it does not enhance the diagnostic accuracy provided by cardiac troponin." (PMID 39175627, 2024). "Clinical research on S100A8/A9 in early warning after PCI for acute myocardial infarction." (PMID 39175627, 2024). "More importantly, short‐term ABR‐238901 treatment post‐myocardial infarction has been shown to inhibit inflammation and improve cardiac function, indicating the potential of S100a8/a9 inhibitor as an immunomodulatory treatment of cardiotoxicity in cancer patients undergoing chemotherapy." (PMID 38023700, 2023). "Importantly, S100A8/A9 binding to TLR-4 has been shown to have a cardio-depressant effect in myocardial infarction by direct inhibition of mitochondrial function in cardiomyocytes." (PMID 37773186, 2023). "In addition, following myocardial infarction, S100A8/A9 downregulates the expression of electron transport chain complex I genes (NDUFs) through the TLR-4/Erk-mediated Pparg coactivator 1 alpha/nuclear respiratory factor 1 signaling pathway." (PMID 37217870, 2023). "S100a8/a9 is constitutively expressed in myeloid cells, especially neutrophils, but its expression can be induced in non‐myeloid cell types in the heart upon stimulations such as myocardial infarction and angiotensin‐II infusion." (PMID 38023700, 2023). "Therefore, S100A8/A9 appears of great significance for the treatment of myocardial infarction and early myocardial ischemia–reperfusion." (PMID 37217870, 2023). "In addition to myocardial tissue, S100a8 and S100a9 are also highly expressed in the blood of patients with acute myocardial infarction." (PMID 35741040, 2022). "Neutrophilia, characterized by elevated neutrophil counts, is linked to the S100A8/A9-NLRP3-IL-1β pathway, which is relevant in myocardial infarction (MI)." (PMID 41141324, 2025). "However, the release of S100A8/A9 particles after myocardial infarction depends on NETosis." (PMID 39087342, 2024). "Research has identified S100A8/A9 as a significant biomarker for CVDs such as myocardial infarction (MI)." (PMID 39329929, 2024). "Therefore, interventions that inhibit NETosis, S100A8/A9, and IL‐1β during the acute inflammatory phase after myocardial infarction may exert beneficial effects on the post‐infarction inflammatory process and ventricular remodelling." (PMID 39087342, 2024). "In myocardial infarction (MI) patients, plasma S100A8/A9 levels increase before the classical markers of myocardial injury such as troponin T or creatine kinase and are higher compared with patients suffering from unstable angina." (PMID 24453429, 2013). "A previous study emphasized the primary role of S100A8/9 and their downstream mediators (e.g. NLRP3) in shaping the inflammatory response following myocardial infarction." (PMID 40069854, 2025). "Therefore, future studies should investigate the impact of S100A8/A9 on the cardiac conduction system and autonomic regulation, the role in atrial fibrillation initiation, but also the contribution to ventricular arrhythmias in post-myocardial infarction patients." (PMID 40948795, 2025).
myocardial infarction (continued). "In rats subjected to coronary ligation, the administration of the S100A8/A9 inhibitor ABR-215757 (5 mg/kg, daily for 5 days) led to a notable decrease in fibrotic areas surrounding the myocardial infarction margins and a reduction in NF-κB p65 protein levels." (PMID 39175627, 2024). "S100A8, S100A9 40, 41, and vimentin 42 are recognized as DAMPs in myocardial infarction (MI) and atherosclerosis." (PMID 35173530, 2022). "The present review will attempt to summarize the increasing body of evidence demonstrating the involvement of S100A8 and S100A9 in atherogenesis, plaque vulnerability, myocardial infarction (MI), and heart failure." (PMID 24453429, 2013). "To further examine the mechanism through which colchicine inhibits the proliferation of neutrophils in BM, we explored the role of the S100A8/A9-NLRP3-IL-1β signaling axis, which has been reported to regulate granulopoiesis and improve cardiac function in mouse myocardial infarction models." (PMID 38062310, 2025). "On the same note, troponin expressing myocardial necrosis extent was positively correlated with white blood cells, neutrophils, NLR, S100A8/A9, NETS, and IL-6, strengthening the conclusion that the activated neutrophils contribute to myocyte dysfunction after myocardial infarction." (PMID 38791147, 2024). "In this cluster, troponin, a strong independent predictor in myocardial infarction, was positively correlated only with neutrophil or neutrophil-associated inflammatory molecules (NLR, S100A8/A9, NETS and IL-6) but not with ESR, Ferritin, Fibrinogen, and CRP." (PMID 38791147, 2024). "Here, we found upregulation of S100A8, S100A9, and CEBPD in PBMCs of stable coronary artery disease/myocardial infarction (sCAD/MI) cases, compared against controls, together with a positive correlation of S100A8 and S100A9 expression with that of CEBPD in these cells." (PMID 35543413, 2022). "Increased plasma levels of S100A9 was a predictor for future nonfatal myocardial infarction among healthy women and S100A8/A9 heterocomplex was found to be an early marker for detection of acute coronary syndrome." (PMID 23209553, 2012).
asthma (40 papers, 2008 to 2025). "S100A8/A9 is involved in innate immune responses in Baker’s asthma pathogenesis and is regulated by TLR4 polymorphisms." (PMID 37110453, 2023). "Elevated levels of S100A8/A9 have been linked to airway hyperresponsiveness in asthma." (PMID 40723384, 2025). "The increased expression of S100A8 was demonstrated in peripheral blood mononuclear cells at the time of asthma exacerbation, while additional S100A9 was elevated in neutrophils and macrophages in patients with untreated asthma." (PMID 40723867, 2025). "Their increased activity is found in the sputum of patients with asthma, which translates into the presence of the S100A8/S100A9 complex, which is largely correlated with the severity of the disease." (PMID 40723867, 2025). "In expression feature analyses, we observe universal upregulation of S100A8, S100A9, S100A12, and RETN in various cell types of asthma patients, particularly S100A8 and S100A9." (PMID 41550933, 2025). "The S100A8/A9 heterodimer plays a dual role in asthma pathogenesis, depending on the inflammatory milieu and asthma subtype." (PMID 41164170, 2025). "Until now, S100A4, S100A8/S100A9 (calprotectin), S100A11, and S100A12 have been implicated in the pathophysiology of asthma, exhibiting both similarities and differences in their mechanisms of action." (PMID 41164170, 2025). "A study using an asthma murine model challenged with A. fumigatus mixed with OVA showed that neutralizing antibodies against S100A8 and S100A9 alleviated airway inflammation and eosinophil recruitment." (PMID 37996952, 2023). "S100A8 and S100A9 are alarmins implicated in various chronic inflammatory conditions, including asthma." (PMID 35837410, 2022). "S100A8 gene expression is increased in blood samples obtained from children with asthma, and S100A9 is increased in the sputum of patients with asthma and COPD." (PMID 32973796, 2020). "The sputum from ACO patients showed an increase in the levels of LL-37 and S100A8 proteins compared to that of asthma patients, whereas the levels decreased compared to those of COPD patients." (PMID 31848359, 2019). "Increased levels of several DAMPs, including HMGB1, HSPs, and S100A8, have been observed in induced sputum and serum of asthma and COPD patients in our and other previous studies that are implicated in the pathogenesis of asthma and COPD." (PMID 31848359, 2019). "S100A8 and S100A9 are important pathogenic mediators in severe asthma because airway resident cells express TLR4, which binds to S100A8 and S100A9, and because both proteins induce pro-inflammatory responses." (PMID 25973752, 2015). "In contrast, in allergic, Th2-driven asthma, S100A8/A9 exerts a regulatory function." (PMID 41164170, 2025). "In addition, elevated expression of S100A8/9 was observed in lungs of mouse model of asthma, a finding that aligns with observations in human asthma patients." (PMID 41164170, 2025). "Conversely, S100A8 could alleviate asthma symptoms by modulating mast cells activation and eosinophil recruitment." (PMID 39809743, 2025). "Importantly, antimicrobial peptides (AMPs) such as hBD-2 and S100A8/A9 are not only relevant to exercise-induced bronchoconstriction (EIB) but implicated in other obstructive airway diseases, including asthma and allergic inflammation." (PMID 40723384, 2025). "Recently, some studies explored the role of S100A8 in the pathogenesis of asthma and COPD." (PMID 31848359, 2019). "Similarly, S100A8 levels in the asthma, COPD, and ACO groups (647.70 ± 56.68, 1241.93 ± 107.39, and 910.76 ± 104.17 ng/mL, respectively) were significantly elevated compared to the NS (385.68 ± 63.18 ng/mL) and HS groups (456.25 ± 62.68 ng/mL)." (PMID 31848359, 2019). "S100A8 down-regulates leukocyte adhesion and negatively regulates phagocyte transmigration, suppresses mast cell activation by scavenging ROS essential for signaling and inhibits acute murine asthma." (PMID 25098409, 2014).